SH3GL2 (SH3 domain containing GRB2 like 2, endophilin A1)
Description:
Implicated in endocytosis. Involved ultrafast endocytosis, by mediating, in a first step, neck formation and in a second step, aids in the removal of clathrin coats from the regenerated vesicles. May recruit other proteins to membranes with high curvature. Required for BDNF-dependent dendrite outgrowth. Cooperates with SH3GL2 to mediate BDNF-NTRK2 early endocytic trafficking and signaling from early endosomes.
Synonyms: CNSA2; SH3D2A; SH3P4; EEN-B1
Tractability: Small molecule: it has a binding pocket of medium quality. Antibody: its Gene Ontology location is reachable by antibodies, with high confidence; UniProt places it where antibodies can reach, with medium confidence. PROTAC: ubiquitination databases record sites on it; its protein half-life has been measured.
Gene: Protein-coding gene on chromosome 9 (17,579,066 to 17,797,129, forward strand). Ensembl gene ENSG00000107295.
Subcellular location: Cytoplasm; Membrane; Early endosome; Presynapse
Subcellular location (Human Protein Atlas): Microtubules; Cytokinetic bridge; Mitotic spindle
Pathways (Reactome):
Vesicle-mediated transport: Cargo recognition for clathrin-mediated endocytosis; Clathrin-mediated endocytosis; Golgi Associated Vesicle Biogenesis; Lysosome Vesicle Biogenesis
Signal Transduction: EGFR downregulation; Negative regulation of MET activity; Retrograde neurotrophin signalling
Developmental Biology: Recycling pathway of L1
Disease: InlB-mediated entry of Listeria monocytogenes into host cell
Immune System: MHC class II antigen presentation
Gene Ontology:
Molecular function: identical protein binding; protein binding; protein-macromolecule adaptor activity
Biological process: negative regulation of blood-brain barrier permeability; negative regulation of epidermal growth factor receptor signaling pathway; negative regulation of gene expression; negative regulation of MAPK cascade; cellular response to brain-derived neurotrophic factor stimulus; central nervous system development; dendrite extension; membrane tubulation; neuron projection development; signal transduction; synaptic vesicle endocytosis; postsynaptic actin cytoskeleton organization
Cellular component: perinuclear region of cytoplasm; clathrin-coated endocytic vesicle membrane; cytoplasm; cytosol; early endosome; glutamatergic synapse; Golgi membrane; membrane; plasma membrane; presynapse; photoreceptor ribbon synapse; postsynapse; presynaptic cytosol
Genetic constraint (gnomAD): Loss-of-function variants: 19 observed, 29.75 expected, observed/expected ratio (o/e) 0.64, 90% interval 0.44 to 0.94. The upper end of that interval is the gene's LOEUF score, 0.94, which puts it in group 3 of 6, group 1 being the genes least tolerant of losing a copy. Missense variants: 302 observed, 300.22 expected, observed/expected ratio (o/e) 1.01, 90% interval 0.92 to 1.11. Synonymous variants: 135 observed, 107.5 expected, observed/expected ratio (o/e) 1.26, 90% interval 1.09 to 1.45.
Homologues: Orthologues: chimpanzee SH3GL2 (100% identical), mouse Sh3gl2 (99% identical), rabbit SH3GL2 (98% identical), dog SH3GL2 (97% identical), rat Sh3gl2 (96% identical), macaque SH3GL2 (96% identical), pig SH3GL2 (95% identical), guinea pig SH3GL2 (93% identical), zebrafish sh3gl2a (75% identical), zebrafish sh3gl2b (51% identical), Drosophila melanogaster EndoB (24% identical), Caenorhabditis elegans F35A5.8 (23% identical), and 3 more. Paralogues in human: SH3GL1 (73% identical), SH3GL3 (68% identical), SH3GLB2 (27% identical), SH3GLB1 (26% identical), SORBS1 (24% identical), SORBS2 (20% identical), SH3D19 (20% identical), SH3RF3 (17% identical), SH3RF1 (17% identical), SORBS3 (17% identical), NCF4 (16% identical), SH3RF2 (11% identical).
Diseases named in the same sentence as SH3GL2 in open-access papers:
SH3GL2 is named in the same sentence as 49 diseases in open-access papers, as found by Europe PMC text mining. Sharing a sentence is not in itself a finding about the gene and the disease. The quoted sentences say what the papers report.
glioma (11 papers, 2016 to 2025). A benign or malignant brain and spinal cord tumor that arises from glial cells (astrocytes, oligodendrocytes, ependymal cells). "In this study, we tried to investigate the role of SH3GL2 in glioma cell migration and invasion and explore its underlined molecular mechanism." (PMID 28470949, 2017). "Loss of SH3GL2 may therefore contribute to migration and invasion of glioma cells." (PMID 36776000, 2023). "Therefore, loss of SH3GL2 may be an critical factor in the occurrence and malignant progression of glioma." (PMID 28470949, 2017). "Other fc3 genes in the curated set, FERMT1, TMEM100, DYNLT3, EPHB1, IGFBP2, NNMT, and SH3GL2 all show direct evidence to a relationship with glioma biology and patient prognosis." (PMID 39941811, 2025). "Another study on SH3GL2 in glioblastoma confirmed its role in suppressing glioma cell migration and invasion." (PMID 36776000, 2023). "SH3GL2, as a suppressor for tumors, and has reduced expression in glioma tissues promoting migration and infiltration of glioma cells by enhancing STAT3/MMP2 signaling." (PMID 32328342, 2020). "SH3GL2 is targeted by mir330, which promotes malignancy in glioma cell lines, suggesting that reduced expression of SH3GL2 results in more aggressive tumors." (PMID 29983870, 2018). "Firstly, we discovered that the protein level of SH3GL2 was widely decreased in the human glioma patients, especially in high‐grade glioma tissues." (PMID 28470949, 2017). "As high‐grade glioma usually has a strong ability of invasion, we focused on exploring the possible roles of SH3GL2 in the migration and invasion of glioma cells." (PMID 28470949, 2017). "The expression level of SH3GL2 was dramatically decreased in glioma tissues, especially in high‐grade glioma tissues (grades II‐IV)." (PMID 28470949, 2017). "In this study, we tried to elaborate the molecular mechanism of SH3GL2 in glioma cell migration and invasion." (PMID 28470949, 2017). "The obtained results proved that knocking down of SH3GL2 markedly aggravated the migration and invasion of glioma cells by activating the STAT3 signalling thereby promoting the expression and secretion of MMP2." (PMID 28470949, 2017). "Immunohistochemical analysis also showed that expression of SH3GL2 was significantly decreased in glioma tissues compared to non‐tumorous tissues." (PMID 28470949, 2017). "It was showed that knocking down of SH3GL2 promoted the migration and invasion of glioma cells, whereas overexpression of SH3GL2 inhibited them." (PMID 28470949, 2017). "In this study, we firstly examined the protein expression of SH3GL2 in glioma patients and glioma cell lines by Western blotting and immunohistochemistry." (PMID 28470949, 2017). "The results showed that the expression of SH3GL2 in glioma cell lines was dramatically decreased compared to the non‐tumorous cell line 293T, especially in U87 cell line with a higher degree of malignancy." (PMID 28470949, 2017). "Then, we determined the role of SH3GL2 in migration and invasion of glioma cells upon SH3GL2 knocking down and overexpressing." (PMID 28470949, 2017). "In this study, we discovered that the protein expression of SH3GL2 was widely suppressed in glioma patients, especially in high‐grade glioma patients." (PMID 28470949, 2017). "Then, the role of SH3GL2 in the migration and invasion glioma cells was investigated through silencing or overexpressing approaches." (PMID 28470949, 2017). "We determined that RRM2 and COL3A1 were increased and directly correlated with glioma grade, while SH3GL2 and SNAP91 were decreased in GBM and inversely correlated with glioma grade." (PMID 27655637, 2016). "We determined that RRM2 and COL3A1 were up-regulated and directly correlated with glioma grade, while SH3GL2 and SNAP91 were down-regulated in GBM and inversely correlated with glioma grade." (PMID 27655637, 2016).
glioma (continued). "Finally, qRT-PCR and IHC analysis confirmed the differential expression of SH3GL2 in tissues of different origin and its correlation with the prognosis of patients with glioma." (PMID 36408514, 2022). "Taken together, these results illustrate that SH3GL2 may play an important role in inhibiting glioma cell migration and invasion by suppressing STAT3/MMP2 signalling pathway." (PMID 28470949, 2017). "Meanwhile, we have demonstrated miR-330 could promote cellular proliferation, migration and invasion of glioma U87 and U251 cells and glioma stem cells by targeting SH3GL2." (PMID 29311822, 2017). "Furthermore, we examined the SH3GL2 expression level in non‐tumorous cell line (293T) and a variety of glioma cell lines (U251, U87, A172, U118 and C6)." (PMID 28470949, 2017). "Based on these knowledge,we speculated that SH3GL2 might negatively regulate STAT3 which would affect the expression of MMP2 in human glioma cells." (PMID 28470949, 2017). "Therefore, we speculate that STAT3/MMP2 signalling may be involved in SH3GL2 mediated migration and invasion of glioma cells." (PMID 28470949, 2017). "To further determine the role of SH3GL2 in glioma cell migration and invasion, we then transiently transfected 3*FLAG‐tagged SH3GL2 cDNA into U87 cells to achieve the gain‐of function." (PMID 28470949, 2017). "SH3GL2 (Src homology 3 (SH3) domain GRB2‐like 2) is mainly expressed in the central nervous system and regarded as a tumour suppressor in human glioma." (PMID 28470949, 2017). "Finally, qRT-PCR confirmed that SH3GL2 and SRGAP3 expression levels in glioma tissues were significantly lower than those in normal brain tissues." (PMID 36408514, 2022). "Expression of SH3GL2 and SNAP91 also inversely correlated with glioma grade." (PMID 27655637, 2016). "However, the molecular mechanism of the SH3GL2 protein involved in malignant behaviours of human glioma has not been elucidated." (PMID 28470949, 2017). "Expression of down-regulated DEGs SH3GL2 and SNAP91, which were found to be >2-fold lower in GBM samples by microarray analysis, was lower in malignant gliomas compared to non-tumor tissue and lower grade gliomas." (PMID 27655637, 2016).
Parkinson disease (11 papers, 2011 to 2025). A progressive degenerative disorder of the central nervous system characterized by loss of dopamine producing neurons in the substantia nigra and the presence of Lewy bodies in the substantia nigra and locus coeruleus. "The gene encoding endophilin A1 (gene name sh3gl2) is almost exclusively expressed in the brain, and has been implicated in epilepsy, schizophrenia, depression, Parkinson’s disease, and Alzheimer’s disease." (PMID 41036704, 2025). "Now we showed for the first time that a Parkinson’s disease risk mutation in SH3GL2 affects autophagy induction at synapses, providing further insight on how synaptic dysfunction is connected to neurodegeneration." (PMID 37067454, 2024). "In vivo analysis in Drosophila showed that the Parkinson’s disease risk variant affects SH3GL2 mobility, subsynaptic localization and calcium influx-dependent autophagy." (PMID 37067454, 2024). "Interestingly, recent GWAS (genome-wide association study) studies have identified variations in the SH3GL2 locus, coding for SH3GL2 (SH3 domain containing GRB2 like 2, endophilin A1), which are associated with increased risk to develop Parkinson’s disease." (PMID 37067454, 2024). "Finally, DNAJC6, SYNJ1 and SH3GL2 are associated with the disruption of synaptic vesicle endocytosis, which contributes to mitochondrial dysfunction and is thus related to the pathogenesis of Parkinson’s disease." (PMID 33686350, 2021). "We discovered that a novel Parkinson’s disease-risk mutation in SH3GL2 (SH3 domain containing GRB2 like 2, endophilin A1) disrupts the calcium sensing of SH3GL2, leading to an immobile protein that cannot respond to calcium influx and therefore disrupting autophagy induction at synapses." (PMID 37067454, 2024). "In fact, variants at numerous other genetic loci related to endocytic trafficking and synaptic maintenance have been discovered as risk factors for Alzheimer’s disease (BIN1, PICALM, CD2AP, SORL1) and Parkinson’s disease (SNCA, LRRK2, SH3GL2/EndoA, RAB7L1)." (PMID 32286230, 2020).
glioblastoma (6 papers, 2014 to 2025). The most malignant astrocytic tumor (WHO grade IV). "Increased ERK, but also Akt signaling, is also observed in SH3GL2 low-expressing glioblastoma stem cells, which correlates with increased proliferation, migration, and invasion." (PMID 40986063, 2025). "Compared to healthy tissues, SH3GL2 expression is decreased in different brain cancer types, including glioblastoma, neuroblastoma, and pilocytic astrocytoma." (PMID 40986063, 2025). "In conclusion, we have presented the first evidence linking SH3GL2 to malignant behaviours of human glioblastoma through STAT3/MMP2 pathway." (PMID 28470949, 2017). "However, miRNA-330 overexpression promoted cellular proliferation of glioblastoma through directly targeting the 3′UTR of SH3GL2 gene." (PMID 33732103, 2021). "Conversely, RNAs overexpressed in LTCs vs LTPs showed an enrichment in markers of the neural subtype of glioblastoma, such as BASP1, CDC42, and SH3GL2." (PMID 26188123, 2015). "However, the molecular mechanisms of the SH3GL2 protein involved in human glioblastoma are not completed clear, which need to be further clarified." (PMID 28470949, 2017).
breast carcinoma (5 papers, 2014 to 2024). "In fact, SH3GL2 expression is frequently lost, and its downregulation is associated with breast cancer progression." (PMID 31052256, 2019). "Consistent with this possibility, analyses in head and neck squamous cell carcinoma, breast carcinoma, laryngeal carcinoma and urothelial carcinoma have implicated SH3GL2 as a candidate tumor suppressor." (PMID 24736727, 2014). "SPANXB1 overexpressing breast cancer cells with an enhanced SPANXB1:SH3GL2 ratio achieved pulmonary metastasis within 5 weeks, whereas controls cells failed to do so." (PMID 31406142, 2019). "Endophilin A1, which is encoded by the SH3GL2 gene, is a vesicular endocytosis-associated protein that could be a breast cancer suppressor." (PMID 31052256, 2019).
head and neck squamous cell carcinoma (4 papers, 2013 to 2020). A squamous cell carcinoma that arises from any of the following anatomic sites: lip and oral cavity, nasal cavity, paranasal sinuses, pharynx, larynx, and salivary glands. "SH3GL2 is a positive prognostic factor in head and neck squamous cell carcinoma and is more highly expressed in exceptional responders." (PMID 29983870, 2018).
urothelial carcinoma (4 papers, 2014 to 2025). A malignant neoplasm derived from the transitional epithelium of the urinary tract (urinary bladder, ureter, urethra, or renal pelvis). "Further suggesting tumor suppressor features, exogenous SH3GL2 expression in urothelial carcinoma, lung adenocarcinoma, and glioma cells decreases their proliferation and migration." (PMID 40986063, 2025). "In urothelial carcinoma, deletion of the gene SH3GL2 is known to promote malignant behavior, meanwhile while DMBT1 has been proposed as a tumor suppressor in brain cancers." (PMID 36352274, 2022). "Indeed, reduced SH3GL2 expression correlates with increased tumor grade and invasion in urothelial carcinoma, and with higher tumor malignancy in vulvar squamous cell carcinoma tissues." (PMID 40986063, 2025).
laryngeal carcinoma (3 papers, 2014 to 2017). Carcinoma that arises from the laryngeal epithelium. "There is some prior evidence to support SH3GL2 as a HNSCC TSG in that its decreased expression and/or deletion was associated with laryngeal cancer." (PMID 26247464, 2015). "It has been confirmed that SH3GL2 displayed a decreased expression level in many tumors such as non-small lung cancer and laryngeal carcinoma." (PMID 24736727, 2014).
Obesity (3 papers, 2014 to 2025). Accumulation of substantial excess body fat. "The SH3GL2 gene is involved in synaptic vesicle endocytosis and lipid binding and modification and, together with CNTLN, has been associated with an obesity index in pigs." (PMID 40646437, 2025).
pilocytic astrocytoma (3 papers, 2013 to 2022). Pilocytic astrocytoma is a rare subtype of low-grade glioma of the central nervous system characterized by a well circumscribed, often cystic, brain tumor with a discrete mural nodule and long, hair-like projections that extend from the neoplastic astrocytes. "SH3GL2 exhibited an important role in clathrin-mediated endocytosis and its underexpression caused pediatric pilocytic astrocytoma." (PMID 35571016, 2022). "Frequent deletion (31–38%) and promoter methylation (34–36%) of SH3GL2 has been reported in breast and lung carcinoma and also deletion in pituitary adenoma, neuroblastoma and pilocytic astrocytoma." (PMID 23675485, 2013).
lung carcinoma (2 papers, 2013 to 2014). "Santanu also reported that genomic loss of SH3GL2 and its expression appeared to be an important and common inactivation event in lung cancer progression." (PMID 24736727, 2014).
malignant glioma (2 papers, 2016 to 2017). A grade III or grade IV glioma arising from the central nervous system. "However, more deeply studies are needed to clarify the precise mechanisms of SH3GL2‐mediated migration and SH3GL2‐mediated invasion in human malignant glioma." (PMID 28470949, 2017).
alcoholism (1 paper, 2012). "Also noteworthy is that SH3GL2 and FHIT, two of the clock modulator genes that are both illness-associated and lithium-responsive, are located within two chromosomal areas (9p22.2 and 3p14) associated with comorbid BD and alcoholism." (PMID 22384149, 2012).
bladder cancer (1 paper, 2017). "They demonstrated that Sh3gl2 expression significantly declined in early-stage as well as in advanced bladder cancer, and silencing Sh3gl2 increased tumor volume." (PMID 28915710, 2017).
cholangiocarcinoma (1 paper, 2022). A carcinoma that arises from the intrahepatic biliary tree (intrahepatic cholangiocarcinoma) or from the junction, or adjacent to the junction, of the right and left hepatic ducts (hilar cholangiocarcinoma). "A previous study demonstrated that circ-CCAC1 elevated YY1 expression to promote cholangiocarcinoma (CCA) by sponging miR-514a-5p in CCA cells while elevating SH3GL2 expression to enhance cell permeability by directly sequestering EZH2 in the cytoplasm of human umbilical vein endothelial cells." (PMID 35045883, 2022).
cognitive decline (1 paper, 2018). "Thus, the observed difference in spatial learning and memory of Tg Sh3gl2/mAPP mice is a result of cognitive decline, which is not due to alteration in motility or motivation." (PMID 30061577, 2018).
epilepsy (1 paper, 2025). A brain disorder characterized by episodes of abnormally increased neuronal discharge resulting in transient episodes of sensory or motor neurological dysfunction, or psychic dysfunction. "To investigate the role of endophilin A1 in epilepsy, we determined the impact of sh3gl2 gene ablation on chemical kindling of pan-neural EndoA1 KO mice with PTZ at a sub-convulsive dose of 25 mg/kg." (PMID 41036704, 2025).
esophageal cancer (1 paper, 2020). A primary or metastatic malignant neoplasm involving the esophagus. "Comprehensive landscape analysis of the staging mechanism of esophageal cancer revealed that the key gene SH3GL2 of ncRNA has-miR-330-3p regulates module 8, which is also a consensus gene in four stages of DEGs." (PMID 32068233, 2020). "Notably, has-miR-330-3p regulates the up-regulated DEG SH3GL2 throughout the esophageal cancer process, suggesting that hsa-miR-330-3p plays a crucial role in four stages of esophageal cancer." (PMID 32068233, 2020).